SCT (secretin)
Diseases named in the same sentence as SCT in open-access papers (continued):
Sharing a sentence is not in itself a finding about the gene and the disease.
cyst (4 papers, 2008 to 2024). A sac-like closed membranous structure that may be empty or contain fluid or amorphous material. "These cystic structures expand spontaneously over time as a consequence of secretion to the cyst lumen, and are able to accelerate their expansion rate with secretin." (PMID 22194894, 2011). "In fact, our findings with Ae2 silencing strongly suggest that the cyst expansion stimulated by TUDCA and/or secretin entails bicarbonate-rich hydroionic secretion into the cyst lumen." (PMID 22194894, 2011). "They expand spontaneously as a consequence of hydroionic secretion to the cyst lumen, and accelerate their expansion rate in the presence of secretin." (PMID 22194894, 2011). "The cyst mucosa showed numerous endocrine cells located in the gastric glands (gastrin, somatostatin and serotonin), the duodenal glands (serotonin, somatostatin, secretin, gastrin and bombesin) and the small-intestinal glands (serotonin, somatostatin, secretin and bombesin)." (PMID 18498655, 2008). "Before removal, imaging techniques (preferably secretin-enhanced MRCP) should confirm the absence of a pancreatic duct ‘feeding’ the cyst." (PMID 39599919, 2024).
migraine (4 papers, 2019 to 2024). "Other peptides being evaluated in the context of migraine are secretin peptides such as pituitary adenylate cyclase-activating polypeptide (PACAP) and vasoactive intestinal peptide (VIP), and to a lesser extent, other peptides in the same class." (PMID 39336867, 2024). "sCT has recently been shown to have the ability to attenuate migraine-like pains by c-fos expression and regulating the release of calcitonin gene-related peptide at different levels." (PMID 31218879, 2019). "By updating our knowledge of PACAP and its unique contribution to migraine pathophysiology, we can pave the way for reinforcing PACAP and other secretin peptides, including VIP, as a novel treatment option for migraines." (PMID 37998384, 2023). "Therapeutic monoclonal antibodies against several classes of GPCRs have been described including secretin-class GPCRs,41 one example being AMG 334 (Erenumab) targeting the Calcitonin Gene-Related Peptide Receptor42 which has now reached the market and is used in migraine prevention." (PMID 31594997, 2019).
Osteopenia (3 papers, 2016 to 2024). Osteopenia is a term to define bone density that is not normal but also not as low as osteoporosis. "Here we show that the loss of ventromedial hypothalamus-derived secretin leads to osteopenia in male and female mice, which is primarily induced by diminished cAMP response element-binding protein phosphorylation and upregulation in peripheral sympathetic activity." (PMID 38310104, 2024). "The secretin concentrations of postmenopausal women with normal bone mass and osteopenia patients differed significantly (P < 0.05)." (PMID 27347465, 2016). "Results also showed that the normal bone mass group had significantly higher secretin signals than that of osteopenia group by ELISA." (PMID 27347465, 2016). "Result showed that the normal bone mass group had significantly higher secretin signals than that of osteopenia group." (PMID 27347465, 2016). "Perhaps the lower secretin in the osteopenia implied less buffering of gastric acid, which could thereby inhibit calcium absorption." (PMID 27347465, 2016). "We speculate that the Secretin (SECR_HUMAN, P09683, Chain: 28–54, pI: 9.46, Mw: 3040) would be potential biomarker for forecasting osteopenia in postmenopausal women." (PMID 27347465, 2016).
Pancreatic cysts (3 papers, 2014 to 2022). A cyst of the pancreas that possess a lining of mucous epithelium. "GNAS mutations have also been previously reported in IPMN cases that had pancreatic cysts with a detection rate of 41–66% from resected tissues, pancreatic cyst fluids, or secretin-stimulated pancreatic juice collected from the duodenum." (PMID 24897499, 2014). "However, the diagnostic utility of secretin in the diagnosis of pancreatic cysts remains debated in part because there have not been controlled studies assessing the added diagnostic value of secretin." (PMID 27628744, 2016).
pancreatic ductal adenocarcinoma (3 papers, 1997 to 2023). An infiltrating adenocarcinoma that arises from the epithelial cells of the pancreas. "We previously demonstrated that the diagnostic performance of PJC was improved via synthetic secretin loading in pancreatic ductal carcinoma." (PMID 35328297, 2022).
primary biliary cholangitis (3 papers, 2011 to 2022). Primary biliary cholangitis (PBC) is a chronic and slowly progressive cholestatic liver disease of autoimmune etiology characterized by injury of the intrahepatic bile ducts that may eventually lead to liver failure. "Secretin induces bicarbonate-rich hydrocholeresis in healthy individuals, but not in untreated patients with primary biliary cirrhosis (PBC)." (PMID 22194894, 2011). "In human-acquired cholangiopathies, like primary biliary cholangitis (PBC) and primary sclerosing cholangitis (PSC), the expression and function of AE2 and secretin are decreasing, and this process induces choleresis." (PMID 35226290, 2022).
acute pancreatitis (2 papers, 2013 to 2020). An acute inflammatory process that leads to necrosis of the pancreatic parenchyma. "The prevalence of pancreatic duct disruption in severe acute pancreatitis (SAP) has been reported to range from 10% to 31% by EPCP or secretin MRCP." (PMID 24015276, 2013). "The prevalence of pancreatic duct disruption in patients with severe acute pancreatitis (SAP) was reported to range from 10% to 31% by EPCP or secretin MRCP." (PMID 24015276, 2013).
depression (2 papers, 2022 to 2023). "Our findings may pave the way for future studies to determine the detailed mechanisms underlying sCT in regulation of the p38 signals, and shed light on potential targeted therapeutic strategies for depression." (PMID 36969556, 2023). "In this study, we delineated the potential role of the calcitonin–AMYR axis in depression by exploiting both the agonist (e.g., sCT) and the inhibitor/antagonist of AMYR (e.g., AC187)." (PMID 35237169, 2022). "Here, the antidepressant potential of salmon calcitonin (sCT) was first evaluated in a chronic restraint stress (CRS) mouse model of depression." (PMID 35237169, 2022). "sCT is an agonist of AMYRs (i.e., AMYR polypeptide), and its role in depression remains to be elucidated." (PMID 35237169, 2022). "Although no changes of CTR expression have been observed in various depression-associated brain regions in the stressed mice, the AMYR antagonist, AC187, potently reversed the antidepressant effect of sCT, suggesting the AMYR-function-dependent role of sCT." (PMID 35237169, 2022).
heart failure (2 papers, 2021 to 2022). Inability of the heart to pump blood at an adequate rate to meet tissue metabolic requirements. "In the early 1980s, intravenous secretin infusion was shown to increase cardiac output and stroke volume in patients with heart failure and patients with angina, but normal ventricular function." (PMID 34806426, 2022). "Based on the present findings, we believe that larger studies are warranted to investigate whether secretin may have a place in the future treatment of heart failure." (PMID 34806426, 2022).
adenoma (1 paper, 2022). A neoplasm arising from the epithelium. "The E proteins E12, E47, and HEB are known to be expressed in SI crypts and adenomas, and E12 and E47 bind to NEUROD1 to induce transcription of secretin in the duodenum." (PMID 35503250, 2022).
alcohol use disorder (1 paper, 2021). "Moreover, sCT, or a selective AMYR agonist, reduce alcohol intake in various models of alcohol use disorder in male and female rats." (PMID 34234676, 2021).
Anorexia (1 paper, 2021). Lack of desire to eat (loss of appetite). "In addition, bloating correlated with CgA (r = 0.85, P = 0.03), anorexia correlated with each of secretin (r = −0.91, P = 0.01) and GIP (r = −0.95, P=0.003), and nausea correlated with each of CCK (r= –0.89, P=0.01) and GIP (r= –0.95, P=0.003) in the idiopathic IBS subgroup." (PMID 34055657, 2021).
Anxiety (1 paper, 2022). Intense feelings of nervousness, tension, or panic often arise in response to interpersonal stresses. "Thus, it is thought that sCT or its receptor is not involved in the anxiety-related neural circuits." (PMID 35237169, 2022).
autism spectrum disorder (1 paper, 2023). A spectrum of developmental disorders that includes autism, and Asperger syndrome. "Moreover, the exogenous application of secretin effectively promoted social interest in both healthy and autism spectrum disorder model mice." (PMID 36845323, 2023).
cholera (1 paper, 2023). "The GspD secretin is the outer membrane channel of the bacterial type II secretion system (T2SS) which secrets diverse toxins that cause severe diseases such as diarrhea and cholera." (PMID 37419909, 2023).
chronic heart failure (1 paper, 2022). "Out of the gastric peptides studied, secretin and gastrin-releasing peptide were significantly lower in patients with chronic heart failure than in controls." (PMID 34806426, 2022). "This could indicate a disturbance of secretin secretion in patients with chronic heart failure." (PMID 34806426, 2022).
cystitis (1 paper, 2009). Inflammation of the urinary bladder. "The efflux defect was specific to the UTI89 cystitis isolate, as none of the CFT073 secretin knockout mutants exhibited defects in fluxing out of the bladder cells (data not shown)." (PMID 19270734, 2009).
dry eye (1 paper, 2022). "This review provides an overview of the evidence supporting oxytocin and secretin as the basis for novel treatments of dry eye and ocular pain syndromes." (PMID 38983562, 2022).
dry eye syndrome (1 paper, 2022). A syndrome characterized by dryness of the cornea and conjunctiva. "PubMed was used to search for articles containing combinations of keywords: (oxytocin OR secretin) AND (inflammation OR anti-inflammatory OR pain OR nociception OR trigeminal neuralgia OR eye OR dry eye syndrome OR Sjögren’s syndrome)." (PMID 38983562, 2022). "A role for topical oxytocin and secretin in dry eye syndrome and ocular pain?" (PMID 38983562, 2022).
eating disorder (1 paper, 2023). A broad group of psychological disorders with abnormal eating behaviors leading to physiological effects from overeating or insufficient food intake. "This study uncovers a potential brain mechanism for secretin-induced satiation, bearing prospective clinical significance in dealing with eating disorders." (PMID 36764966, 2023).
esophageal reflux (1 paper, 2005). "Gastroesophageal reflux may contribute to some of the behavioural problems and explain the effect of secretin since its suppressive effect on gastric secretion is well known." (PMID 16287506, 2005). "In our report the child who improved with secretin treatment was the one characterized by reflux esophagitis, while the child who did not improve had chronic diarrhea but no gastric or esophageal reflux." (PMID 16287506, 2005).
gallstones (1 paper, 2020). Solid crystalline precipitates in the biliary tract, usually formed in the gallbladder, resulting in the condition of cholelithiasis. "Cholecystectomy has been shown to be capable of increasing the serum levels of cholecystokinin and secretin, and it is suggested to measure their serum levels before and after the removals of gallstones to ascertain whether this alteration is related to increased risk of prostate cancer." (PMID 32120816, 2020).
Hyperglycemia (1 paper, 2018). An increased concentration of glucose in the blood. "Hyperglycemia has also been reported to suppress the vagovagal reflex that is activated by cholecystokinin and secretin." (PMID 29410956, 2018).
postmenopausal osteoporosis (1 paper, 2015). Metabolic disorder associated with fractures of the femoral neck, vertebrae, and distal forearm. "The objective of the present study was to assess the effectiveness of combined salmon calcitonin (sCT) and aspirin [acetylsalicylic acid (ASA)] treatment in an ovariectomized (OVX) rat model of postmenopausal osteoporosis." (PMID 25891179, 2015).
somatostatinoma (1 paper, 2020). A rare, usually malignant neuroendocrine tumor arizing from delta cells. "In most patients (92.7%), the clinical somatostatinoma syndrome was caused by the inhibition of insulin, glucagon, gastrin, secretin, and somatotrophin." (PMID 33204258, 2020).
urinary tract infection (1 paper, 2009). "We compared the secretin deletion mutants with their wild type counterparts using tissue culture assays and the CBA/J mouse model of ascending urinary tract infection." (PMID 19270734, 2009).
Zollinger-Ellison syndrome (1 paper, 2012). Zollinger-Ellison syndrome (ZES) is characterized by severe peptic disease (ulcers/esophageal disease) caused by hypergastrinemia secondary to a gastrinoma resulting in increased gastric acid secretion. "Using a delta gastrin of 200 pg/mL, the secretin test has a sensitivity and specificity of 82% and 100% for the diagnosis of Zollinger-Ellison syndrome." (PMID 24213225, 2012). "In those Zollinger-Ellison syndrome patients with a negative secretin test the calcium infusion test is positive in 38%–50% of the patients." (PMID 24213225, 2012). "Pylorus-preserving pancreatico-duodenectomy may therefore be justified if there is a biochemical diagnosis of Zollinger-Ellison syndrome in MEN-1 and the source of gastrin can be regionalized by preoperative selective arterial secretin injection to the head of the pancreas." (PMID 24213225, 2012).
tumor (11 papers, 1997 to 2023). "We first used PCR amplification of selected GPCRs starting from cDNA derived from mouse proximal duodenal mucosal scrapings, and from cells of the intestinal STC-1 cell line (Secretin Tumor Cell line - 1) incubated in 5 mM or 25 mM glucose." (PMID 36699012, 2022). "Peptides such as secretin, gastrin, bombesin, cholecystokinin, and vasoactive intestinal peptide are believed to promote the proliferation of tumor cells." (PMID 32056066, 2020). "Secretin tumour cell line 1 enteroendocrine cells were treated for 24 or 48 h with toll-like receptor agonists (toll-like receptor 4 selective lipopolysaccharide; toll-like receptor 2 selective Pam3CysSerLys4) and the free fatty acid receptor 2/3 agonists butyrate, propionate and acetate." (PMID 37953845, 2023). "Consequently, the structure–activity relationship of secretin was investigated by analyzing a library of variants of the natural peptide, with the intent of paving the way for the future development of secretin-based tumor tracers." (PMID 35327338, 2022). "In addition, several cell lines were also established from the primary tumor which we further characterized and found to have a similar cDNA profile like the tumor samples and express chromogranin A, B, as well as secretin and glucagon." (PMID 32373532, 2020). "The arterial secretin injection (SASI) test may contribute to the anatomic localization of the primary tumour in the pancreas and duodenum." (PMID 24213231, 2012). "Chronic secretin stimulation and NOC exposure potentially overwhelm DNA repair capabilities, acting synergistically to induce tumor development." (PMID 32784492, 2020). "The secretin tumour cell line, STC-1, derived from a mouse small intestinal neuroendocrine carcinoma, secretes a variety of small intestinal gut hormones including GIP, GLP-1, secretin and CCK." (PMID 33803183, 2021). "The endocrine cells in the appendix and caecum tumour samples were bombesin-, endorphin-, gastrin- and secretin-negative." (PMID 18252007, 2008).
cancer (7 papers, 2013 to 2025). A tumor composed of atypical neoplastic, often pleomorphic cells that invade other tissues. "Future studies will have to demonstrate the utility of secretin analogues as tracers for molecular imaging and targeted therapy of cancer." (PMID 35327338, 2022). "Secretin (SCT) is an oncogene with an anti-proliferative effect in normal cells but a proliferation-stimulating activity in cancer cells." (PMID 36119505, 2022). "Moreover, we suggest two cancer drugs as potential repurposable candidates for SjD: Tucatinib and Secretin." (PMID 40429780, 2025). "The pathomechanism of thrombus formation in Trousseau’s syndrome is still unestablished; however, it is generally accepted that heparin administration is the preferred treatment, since heparin inhibits the binding between cancer-secreting mucin and secretin which leads to platelet aggregation." (PMID 32388737, 2020). "Receptors for peptides secreted by neuroendocrine cells, such as secretin, gastrin, bombesin, cholecystokinin, and vasoactive intestinal peptide, have been identified in many cancer types, including cancers of lung, ovarian, thyroid, brain, genitourinary and gastrointestinal tract." (PMID 24392036, 2013).
infection (6 papers, 2009 to 2025). The state of being infected such as from the introduction of a foreign agent such as serum, vaccine, antigenic substance or organism. "Upon infection, phage secretin pIV expression stimulates the phage shock response by causing the release of transcription factor pspF from the membrane, which binds to Ppsp and activates it." (PMID 36970395, 2020). "We found that the secretin GspD of the type II secretion system (T2S) of Leptospira interrogans serovar Canicola was highly conserved amongst pathogenic serovars and was expressed in vivo during infection, as shown by immunohistochemistry." (PMID 33327369, 2020). "In this study we have demonstrated that the Leptospira secretin protein, GspD, is expressed in vitro and antigenic during natural infection in canines." (PMID 33733085, 2021). "However, due to the risk of infection, porcine secretin is no longer used in most countries." (PMID 35328297, 2022). "The single secretin knockout mutants of CFT073 also showed no significant defects in colonizing the urinary tract on day 7 post-infection." (PMID 19270734, 2009).
metabolic disease (2 papers, 2022 to 2024). A congenital disorder (due to inherited enzyme abnormality) or acquired (due to failure of a metabolically important organ) disorder resulting from an abnormal metabolic process. "The pituitary adenylate cyclase-activating polypeptide (PACAP)-selective PAC1 receptor (PAC1R) is a member of the vasoactive intestinal peptide (VIP)/secretin/glucagon family of G protein-coupled receptors (GPCRs), which play important roles in metabolic disorders." (PMID 39195547, 2024).
brain disorder (1 paper, 2023). A disease affecting the brain or part of the brain. "More recently, it has also been implied in several brain disorders since its other substrates include neuropeptide Y, secretin, substance PACAP and amyloid peptides." (PMID 36826039, 2023).
endocrine diseases (1 paper, 2022). "The GPCRs-targeted drugs such as GLP-1, which belongs to secretin GPCRs, have been used for the treament of cardiovascular diseases and endocrine diseases." (PMID 36187484, 2022). "Among them, the secretin/adhesion (Class B) G protein-coupled receptors are essential drug targets for human diseases, such as endocrine diseases and cardiometabolic diseases." (PMID 36187484, 2022).
gastrointestinal disorders (1 paper, 2025). "Elevated secretin levels may indicate the presence of excess acidic chyme in the duodenum or gastrointestinal disorders such as inflammation or dysregulated acid secretion." (PMID 40904779, 2025).